ADORA2B (adenosine A2b receptor)
Diseases named in the same sentence as ADORA2B in open-access papers (continued):
Sharing a sentence is not in itself a finding about the gene and the disease.
neuroblastoma (1 paper, 2022). Neuroblastoma (NB) is the most common solid, extracranial childhood tumor. "Interestingly, between human and murine neuroblastoma cells, differences in the ADORA2B and ADORA3 expression pattern can also be observed." (PMID 35216410, 2022).
oral squamous cell carcinoma (1 paper, 2015). "Little is known about the relevance of ADORA2B to human malignancy including oral squamous cell carcinoma (OSCC)." (PMID 26228921, 2015).
osteoarthritis (1 paper, 2012). A noninflammatory degenerative joint disease occurring chiefly in older persons, characterized by degeneration of the articular cartilage, hypertrophy of bone at the margins and changes in the synovial membrane. "However ADORA2B protein was also expressed by vascular ECs with a flattened morphology in osteoarthritis synovium (data not shown)." (PMID 22682496, 2012).
pyelonephritis (1 paper, 2022). An inflammatory process affecting the kidney. "Signaling via adenosine receptors, ADORA2A or ADORA2B, stimulates proton secretion by α‐ICs; thus adenosine production in pyelonephritis‐induced tissue injury may trigger dysregulated urine acidification leading to systemic alkalosis as is the case in GPR116 or ADGRF5‐deficient mice." (PMID 36151614, 2022).
renal cell carcinoma (1 paper, 2020). "Taken together, our results suggest that adenosine A2b receptor blockade may inhibit renal cell carcinoma growth." (PMID 31897237, 2020). "Similarly, the protein level of A2bR was not affected by MRS1754.These findings suggested that adenosine A2b receptor may play an important role in biological behavior of renal cell carcinoma." (PMID 31897237, 2020). "Collectively, high expression of A2bR on RCC cell provides us new understandings of the role of adenosine receptor in tumor progression and blockade of adenosine A2b receptor may act as a promising candidate for therapeutic intervention for renal cell carcinoma." (PMID 31897237, 2020).
sarcoma (1 paper, 2022). A usually aggressive malignant neoplasm of the soft tissue or bone. "Sarcomas had the highest alteration frequencies for ADORA2B gene amplification as well as highest median copy number at DNA level when compared against 33 TCGA tumor types." (PMID 35580926, 2022).
serous carcinoma (1 paper, 2022). "In contrast, for serous carcinoma, the surveillance of both cohorts (482 with low expression vs. 622 with high expression) revealed that the group with reduced ADORA2B had a worse prognosis than the group with high ADORA2B levels (15.80 months vs. 18.60 months, respectively) (p = 0.015)." (PMID 35562985, 2022).
thyroid tumor (1 paper, 2015). A benign or malignant neoplasm affecting the thyroid gland. "We next examined the methylation status of REC8 and ADORA2B in human thyroid tumor tissues." (PMID 26472282, 2015).
ulcers (1 paper, 2025).
tumor (34 papers, 2008 to 2026). "ADORA2B is a gene encoding the adenosine A2B receptor, a member of the adenosine G protein-coupled receptor family that is involved in regulating inflammation, hypoxia responses, and tumor progression." (PMID 41216196, 2025). "MR implicated 26 genes in EC risk; among these, ADORA2B and SAPCD2 were consistently overexpressed in tumors (external validation and RT-qPCR) yet higher tumor expression predicted longer survival." (PMID 42052492, 2026). "• Pan-cancer heterogeneity of CD39, CD73, and ADORA2A, ADORA2B.• Varying concentrations of eAdo in time and space.• eAdo level varies across tumor types." (PMID 41583489, 2025). "This cell-type-specific crosstalk—confined to CD8+ T cells in GC TME—creates a synergistic immunosuppressive loop, where Adora2b and PD-1 mutually reinforce each other’s signaling to impair anti-tumor cytotoxicity." (PMID 41346607, 2025). "From physiological acid secretion to pathological tumor progression, Adora2b thus serves as a critical link between gastric function and immune evasion in GC." (PMID 41346607, 2025). "Here, we find that blockage of cAMP degradation by PDE inhibitors does not affect the growth of SmoM2-induced tumors, but activation of the Gαs-coupled ADORA2B can lead to reduced tumor burden and proliferation." (PMID 40060632, 2025). "Analysis of gene expression in our single-cell BCC data revealed several targetable Gαs-coupled GPCRs present in tumor cells, including prostaglandin E receptor 4 (Ptger4), adenosine receptor 2b (Adora2b) and β-Adrenergic Receptors (Adrb1–2), among others." (PMID 40060632, 2025). "ADORA2A (adenosine A2a receptor) and ADORA2B propagate immunoregulatory signals, including restricting both innate and adaptive immunity, though recent data also suggest a tumor suppressor effect in certain settings." (PMID 38731962, 2024). "ADORA2B-related signaling has been reported to be involved in solid tumor migration mechanisms as well as tumor-derived exosome-induced angiogenesis." (PMID 38732015, 2024). "In this review, we discuss the mechanistic consequences of Adora2b activation on cell types in the tumor microenvironment." (PMID 37187740, 2023). "show the reduction in tumor growth using a small molecule inhibitor of Adora2b is dependent on CD8+ T cells." (PMID 37187740, 2023). "In contrast, expression of genes correlated with worse survival and hypoxia (PANX1, NT5E, ADORA2B, and P2RY2) was associated with tumor cells and the squamous PDAC subtype, correlating with hypoxia, inflammation, and worse prognosis." (PMID 36942939, 2023). "Accordingly, compared with control groups, mice treated with sorafenib in combination with ADORA2B blockage reagents emerged evident inhibition of tumor progression." (PMID 36969014, 2023). "The expression of A2BAR gene (ADORA2B) was investigated using The Cancer Genome Atlas (TCGA)—Pan cancer publicly available dataset across 33 tumor types." (PMID 35580926, 2022). "The accumulation of ADO stimulates tumor growth and metastasis through the binding to ADORAs inducing the downstream signaling of the intracellular cAMP through ADORA2A and ADORA2B, which is associated with immunosuppression." (PMID 35079944, 2022). "ADORA2B also regulates the tumor microenvironment and is involved in peripheral vascular growth, inflammatory cell infiltration, fibroblast proliferation, and extracellular matrix accumulation." (PMID 34350210, 2021). "ADORA2B was reported to be involved in tumor-cell proliferation, tumor-cell metastasis, and tumor microenvironment changes." (PMID 34350210, 2021). "ADORA2B plays an important role in the occurrence, development, and metastasis of human tumors and is expressed in a variety of tumor cells." (PMID 34350210, 2021). "We found that compared with that in normal lung tissues, the expression level of ADORA2B was significantly elevated in tumor tissues of LUAD patients with higher morbidity." (PMID 34350210, 2021).
tumor (continued). "For example, genetic loss or pharmacologic inhibition of CD73 as well as inhibition of ADORA2B reduced the metastatic potential of tumor cells in preclinical studies." (PMID 31623231, 2019). "This suggests that a new molecular sub-classification of TNBC is required, especially among cases with basal-like phenotypes, with tumor growth being driven by an interaction of ADORA2B-signaling with the TME." (PMID 30349649, 2018). "Further examples include the adenosine receptor Adora2b that was shown to play a major role in tumor progression by suppressing tumor specific immune responses as well as connexin 31 also known as gap junction membrane channel protein β3." (PMID 29254206, 2017). "A possible explanation for this discrepancy is that ADORA2B proteins are differently affected by the post-translational ubiquitination and proteolysis in each tumor cell lines." (PMID 26228921, 2015). "However, Adora2b activation inhibits DC migration, preventing them from initiating CD8+ T-cell and Th1 responses; blocking Adora2b reverses this, enhancing anti-tumor immunity." (PMID 41346607, 2025). "In addition, Adora2b expression is increased in tumor cells in BCC mice when compared to control mice, while β-adrenergic receptor expression is reduced." (PMID 40060632, 2025). "Finally, we demonstrate that activation of the Gαs-coupled GPCR adenosine 2b receptor (ADORA2B) reduces tumor formation in a BCC mouse model." (PMID 40060632, 2025). "Notably, Adora2b homodimers in GC strengthen downstream pro-tumor signaling (e.g., cAMP/PKA pathway activation), amplifying immunosuppression and metastasis compared to heterodimers." (PMID 41346607, 2025). "CD73 is an independent prognostic factor in prostate cancer, as the expression of CD73 in the prostate epithelium suppresses immunosurveillance by CD8+ T cells, while the expression of CD73 in the tumor stroma reduces NF-kB signaling in tumor cells via adenosine A2B receptor." (PMID 39355246, 2024). "In solid tumors with a hypoxic TME, Adora2b antagonists may promote increased infiltration of immune cells and anti-tumor immunity." (PMID 37187740, 2023). "Pharmacologic inhibition of Adora2b also restrained tumor growth in vivo; however, the effect of the small molecule inhibitor was not present in tumor growth in CD8KO mice indicating adenosine signaling through Adora2b significantly restrains CD8+ T cell anti-tumor activity in PDAC." (PMID 37187740, 2023). "The roles of ADORA2B in promoting tumor metastasis have been well characterized; however, the roles of P2RX1 in PDAC progression or metastasis remain unknown." (PMID 33420030, 2021). "In summary, our results indicate that ADORA2B has oncogenic activity both in vitro and in vivo, and suggest that this receptor could be a critical driver of tumor propagation through the adenosine signaling pathway." (PMID 30349649, 2018). "In a similar way – and considering that netrin-1 is pro-angiogenic – our results allow speculatation that ADORA2B could mediate the sprouting of vessels during tumor neovascularization." (PMID 18447899, 2008). "In PDAC, perineural infiltration is present in early and late stages of the disease and neuronal infiltration by tumor cells may contribute to pain and tumor progression indicating Netrin-1/Adora2b signaling could be evaluated as a therapeutic strategy to reduce perineural infiltration." (PMID 37187740, 2023). "Therefore, ADORA2B regulates tumor progression and metastasis and could serve as a useful target for cancer therapy or combination therapy." (PMID 34350210, 2021).
tumor (continued). "IPA revealed that ADORA2B expression was correlated with tumor survival pathways, including the NF-kB and HIF-1 pathways, indicating it may have a role to play in tumorigenicity and metastasis, although such an association has not been previously explored in TNBC." (PMID 30349649, 2018). "It was shown that the Adora2b, inhibitor PSB1115 reduced the number of CAFs expressing fibroblast activating protein (FAP) and fibroblast growth factor (FGF-2) in the tumor microenvironment of melanoma mice." (PMID 41346607, 2025). "The expression of ADORA2B, SERPINE1 and SLC7A1 was definitely higher in tumor stages III-IV compared with tumor stage I-II (P < 0.05)." (PMID 33828988, 2021). "ADORA2B-expression was significantly correlated with ER (P < 0.01), PgR (P = 0.027), EGFR (P < 0.01), and tumor size (P = 0.037), and was an independent prognostic factor for outcome (P = 0.036)." (PMID 30349649, 2018). "Also, in complimentary studies, wild-type mice treated with PSB1115, an Adora2b antagonist, had reduced KPC subcutaneous tumor growth compared to vehicle-treated KPC tumor-bearing mice." (PMID 37187740, 2023). "Adora2b is upregulated on macrophages by IFN-γ and when Adora2b is activated, TNF production in infiltrating macrophages is suppressed, inhibiting their capacity to secrete cytokines important for anti-tumor immunity and promoting tumor growth." (PMID 37187740, 2023). "By coupling ADORA2B to G proteins and through downstream signaling: Gs (via cAMP) Gi (via PI3K) and Gq (via PLC), this receptor promotes different functions in the tumor microenvironment (cell proliferation, angiogenesis, immune suppression, cell invasion and inflammation)." (PMID 35079944, 2022). "The adenosine A2b receptor agonist, BAY 60-6583, was found to significantly increase cytokine secretion of CD133-or HER2-specific CAR T cells when co-cultured with the respective target tumor cells." (PMID 33776765, 2021). "Therefore, we concluded that BAY 60-6583 seems to have multiple targets and that its regulatory roles in CAR T cells when targeting tumor cells were achieved independent of the adenosine A2b receptor." (PMID 33776765, 2021). "For tumor-derived exosomes (TEX), which play an important role in the promotion of tumor angiogenesis, it has just recently been shown that a growth stimulation of endothelial cells (ECs) in vitro and an angiogenic effect in vivo was mainly mediated by the adenosine A2B receptor." (PMID 32545804, 2020). "The adenosine A2b receptor (ADORA2B) belongs to the G protein-coupled adenosine receptor superfamily, and is expressed in the plasma membrane, suggesting it may play a role in interacting with the tumor microenvironment (TME)." (PMID 30349649, 2018). "Clinicopathological analysis showed that high ADORA2B expression has significantly reverse correlation with four important clinical parameters, ER positivity (P < 0.01), PgR positivity (P = 0.027), EGFR positivity (P < 0.01) and tumor size (P = 0.037), but not HER-2 positivity (P = 0.77)." (PMID 30349649, 2018).
cancer (19 papers, 2015 to 2025). A tumor composed of atypical neoplastic, often pleomorphic cells that invade other tissues. "ADORA2B interacts with these proteins that regulate important cellular processes associated with cancers and diseases." (PMID 34350210, 2021). "Adenosine receptor A2B (ADORA2B) encodes an adenosine receptor belonging to the G protein–coupled receptor superfamily and is highly expressed in various carcinomas, which leads to the promotion of carcinoma cell proliferation and metastasis." (PMID 34350210, 2021). "We hypothesized that ADORA2B may be associated with cancer progression." (PMID 26228921, 2015). "It has been reported that ADORA2B can promote the proliferation of various cancer cell types and confer apoptosis resistance by activating the PI3K–Akt signaling pathway." (PMID 41216196, 2025). "In cancer, there are also conflicting studies related to the function of Adora2b in the progression of different malignant diseases." (PMID 37187740, 2023). "Those genes contributing to ‘defense response’ and ‘peptidase activity’ terms in recurrent tissues were mainly composed of a number of genes previously associated with cancer such as S100A8, S100A9, TANK, or ADORA2B." (PMID 37177979, 2023). "Blockade of the adenosine A2B receptor (A2BAR) represents a potential novel strategy for the immunotherapy of cancer." (PMID 35744918, 2022). "Next, we used the cBioPortal database to evaluate the types and frequencies of ADORA2B alterations in LUAD tissues based on sequencing data from patients with LUAD obtained from TCGA’s Pan-Cancer Atlas database." (PMID 34350210, 2021). "An ADORA2B correlation network was constructed to determine the potential mutual effects between ADORA2B and cancer-related targets." (PMID 34350210, 2021). "We further examined the protein expression levels of markers of carcinoma cell proliferation and metastasis after ADORA2B knockdown." (PMID 34350210, 2021). "Further analysis using the UALCAN database showed that the mRNA expression levels of ADORA2B were significantly higher in LUAD samples than in para-carcinoma tissues." (PMID 34350210, 2021). "Previous studies have demonstrated that ADORA2B participates in the proliferation and metastasis of carcinomas." (PMID 34350210, 2021). "Adenosine A2b receptor (A2bR) is a member of the G protein-coupled receptor superfamily members, which has been considered involved in the pathogenesis of various cancers." (PMID 31897237, 2020). "The adenosine A2B receptor has been proposed as a novel therapeutic target in cancer, as its expression is drastically elevated in several tumors and cancer cells." (PMID 32366046, 2020). "Many studies have indicated that ADORA2B plays critical roles, including tumoral development and progression, in cancers." (PMID 26228921, 2015). "In detail, while the ADORA2B-PNP pair is associated to lower survival in uterus, P2RY4 axes with ENPP3 and ENTPD1 are associated to higher survival in the same cancer." (PMID 38723607, 2024). "Therefore, the adenosine A2B receptor is currently in focus as a novel target for cancer therapy as well as for noninvasive molecular imaging via positron emission tomography (PET)." (PMID 34069548, 2021). "Abnormal expression of ADORA2B may play a pathophysiological role in some human cancers." (PMID 34350210, 2021). "Studies above suggested that adenosine A2b receptor may have cancer-promoting properties." (PMID 31897237, 2020).
infection (3 papers, 2015 to 2026). The state of being infected such as from the introduction of a foreign agent such as serum, vaccine, antigenic substance or organism. "Considering that fibrosis is often limited in cases of chronic fascioliasis in sheep compared with cattle, it would be interesting to confirm the role of adora2b during infection by studying its expression in cattle." (PMID 25885344, 2015).
renal disease (3 papers, 2018 to 2023). "Among these genes, Adora2b, Trpc5, Ar, Xrcc2, and Atp1b1 are involved in renal disease and blood pressure regulation." (PMID 37125041, 2023). "Our reports suggest that miR-27b/Adora2b axis play important roles in podocyte injury and could be potential therapeutic targets for podocyte protection in human renal diseases." (PMID 30429458, 2018). "Interestingly, Adora2b, which mediates renal AMP-activated protein kinase (AMPK) activation, and Trpc5, whose abnormal expression was suggested to interfere with progressive kidney diseases, were subsequently altered at the methylation level due to postnatal protein restriction." (PMID 37125041, 2023).
inflammation (2 papers, 2020 to 2022). Aberrant reaction of the microcirculation characterized by movement of fluid and leukocytes from the blood into extravascular tissues. "Further, we revealed the link of the anesthetic agent with a functional Adora2b signaling and evaluated the effects of sevoflurane on HO-1 modulation during acute pulmonary inflammation." (PMID 35406657, 2022).
cardiovascular disease (1 paper, 2020). "ADORA2B also showed a close relationship with cholesterol regulation by formation of foam cells and inflammation, which are mediator of cardiovascular disease." (PMID 32075205, 2020).